ITGB1 (integrin subunit beta 1)
Diseases named in the same sentence as ITGB1 in open-access papers (continued):
Sharing a sentence is not in itself a finding about the gene and the disease.
breast cancer (continued). "Itgb1 is involved in the regulation of cell migration and invasion of hepatoma carcinoma, breast cancer, and gallbladder cancer." (PMID 31791390, 2019). "Higher expression of KLK5 correlated with higher levels of miR-183-5p, lower ITGB1 expression, and a basal-like breast cancer subtype." (PMID 25593998, 2014). "Lower expression of KLK5 and miR-183-5p was correlated with higher ITGB1 expression and a luminal A or B breast cancer subtype in these patients." (PMID 25593998, 2014). "The involvement of some of the genes affecting cancer cell death–Adm, Cflar, Cyr61, Ddit4, Itgb1, Mapk1, Mapk8, Tgfβ2, Tpm1, Vegfα and Wasf1, was demonstrated in breast cancer cell lines." (PMID 19450255, 2009). "ITGB1 expression in breast cancer stem cells was significantly lower than in MCF-7 cells." (PMID 38963646, 2025). "In support, studies have shown that the T188I mutation in ITGB1 contributed to neoplasia by over-activating ERK/MAPK signaling, and mutations in ITGA2 were associated with an increased risk of prostate, oral, and breast cancers." (PMID 39436262, 2024). "Moreover, ITGB1 is involved in TGF-β signaling pathway-mediated metastatic behavior of breast cancer and can switch the tumor suppression function of TGF-β to oncogenesis in prostate cancer." (PMID 38814534, 2024). "Next, to examine whether cardiac remodeling promotes ITGB1 KO tumor growth, we implanted PyMT and ITGB1 KO breast cancer cells into the mammary fat pad of female C57Bl/6 mice." (PMID 38139195, 2023). "Therefore, USP22 controls breast cancer stem cell self-renewal through protecting FoxM1 from ubiquitination-mediated proteasomal degradation to enhance ITGB1 transcription." (PMID 37398311, 2023). "Collectively, our study identified USP22 as a FoxM1-specific deubiquitinase which promotes FoxM1 transcriptional activation for ITGB1 expression, which consequently promotes breast cancer stem cell self-renewal and drives breast cancer metastasis to distal organs including lung." (PMID 37398311, 2023). "Indeed, ITGB1 and ITGB3 have been reported to play an important role in HER-2-induced mammary tumor growth and metastasis to the lungs, and this is associated with the promotion of signaling through the insulin receptor-AKT-mTORC1 pathway." (PMID 37175499, 2023). "Indeed, ectopic ITGB1 expression partially rescued tumor sphere formation from in both mouse 4T1 and patient-derived L2G+ TN1 USP22-deficient breast cancer cells." (PMID 37398311, 2023). "Previous studies have shown that knockdown of ITGB1 reduces breast cancer and colorectal cancer." (PMID 38248716, 2023). "Interrogation of the breast cancer KM plotter datasets showed that, in concordance with WAVE2, increased levels of ITGB1 correlate with decreased survival probability of patients with breast cancer, while increased expression levels of miR-29a and miR-29b have the opposite effect." (PMID 36968231, 2023). "Previous studies confirmed that upregulated SIPA1 in breast cancer cell lines, SIPA1 activates the promoter activity of ITGB1 through transcription, which improves the adhesion ability of breast cancer cells, thereby improving the malignancy of breast cancer cells." (PMID 36230738, 2022). "Interestingly, meta-studies found that the high-level expression of ITGB1 was significantly correlated with the overall survival difference in lung and breast cancer patients." (PMID 36178365, 2022). "ITGB1 is crucial for fascin-mediated breast cancer stem cell function and disease progression." (PMID 33591944, 2021). "Furthermore, 12 breast cancer tissues from patients who received epirubicin treatment were used for immunohistochemistry of ITGB1." (PMID 33747911, 2021).
breast cancer (continued). "Additionally, analysis of whole exome sequencing of tumor biopsies from the Metastatic Breast Cancer Project showed a decrease in copy number of ITGB1 and variable expression of ITGA2 between primary tumors, soft tissue metastases, and bone metastases." (PMID 34199096, 2021). "This was consistent with the results obtained for other cancers, which suggested that linc-ITGB1 could promote the invasion and migration of gallbladder cancer cells, and high expression of ITGB1 could increase the invasion of breast cancer cells." (PMID 33014056, 2020). "Although both breast cancer cells in this study react differently to the ITGB1-kd with respect to DDR1, either by its upregulation (MDA-MB-231) or a slight downregulation (MCF-7), both cell lines confer COL1 binding into an active DDR1-mediated signaling via the MAPK pathway." (PMID 32668815, 2020). "Interestingly, amongst the alternatively spliced genes were very well-known determinants of breast cancer progression, including integrin β1 (ITGB1)." (PMID 30940821, 2019). "Furthermore, targeted disruption of ITGB1 in a transgenic mouse model of human breast cancer inhibited both initiation and maintenance of mammary tumor growth." (PMID 25593998, 2014). "We identified 7 genes (ITGB1, SNAI1, NOTCH4, STAT5B, RAPGEF3, LAMA2, and GNAI1) that have been implicated in both stemness and the drug response and validated their relevance through an analysis of data from breast cancer patients in the TCGA database using UCSC Xena." (PMID 39180549, 2024). "We then focused on studying the functional consequences of USP22-mediated integrin b1 upregulation and assessed whether USP22 maintains breast CSC self-renewal and promotes breast cancer metastasis through integrin b1 upregulation by ectopic reconstitution of ITGB1 in USP22 knockout cells." (PMID 37398311, 2023). "Our data collectively documented that USP22 maintain breast cancer stemness in part through stabilizing ITGB1 transcription factor FoxM1 to promote breast cancer growth and metastasis, which define a previously unknown USP22-FoxM1-ITGB1 pathway in breast cancer pathogenesis." (PMID 37398311, 2023). "Therefore, the mechanism causing breast cancer cell adhesion, migration, and invasion can be explained by SIPA1, which may be achieved by regulating the ITGB1/FAK/Akt-MMP9 signaling pathway." (PMID 36230738, 2022). "Similarly, we observed an increase in the expression of Itgb1 (coding for CD29) and Itga6 (coding for CD49f), together with the upregulation of genes associated with EMT, a key biological process also known to modulate the stemness of breast cancer cells." (PMID 32581213, 2020). "Consistently, a similar but moderate enrichment of human ITGB1 expression was also observed in blood DPT cells versus CD4+ and CD8+ T cells, based on scRNA-Seq data of breast cancer patients." (PMID 40955669, 2025). "To model integrin β1 (hereafter referred to as ITGB1) phosphorylation during invasive breast cancer progression, we knocked down the ITGB1 mRNA in MDA-MB-231 (MM231) breast cancer cells using a lentiviral short-hairpin RNA (shRNA) (MM231 shβ1 cells)." (PMID 40419795, 2025). "Datasets from basal-like breast cancer patients indicated a strong, positive correlation between IGF-1R protein expression and that of β1-integrin (ITGB1)." (PMID 39608716, 2024). "TN-C, a ligand of ITGB1 and ITGB3, is produced by breast cancer cells to encourage CSC self-renewal and to improve their capacity to initiate metastasis." (PMID 38279122, 2024). "Taken together, these data indicate that ITGB1 expression distinctly alters IGF-1R location in less migratory, hormone-responsive MCF-7 cells compared to more aggressive TNBC Hs578T breast cancer cells." (PMID 39608716, 2024). "Interrogation of the cBioPortal breast cancer datasets confirmed the positive correlation in expression levels between WAVE2 and ITGB1 in human breast cancer specimens." (PMID 36968231, 2023).
breast cancer (continued). "SIX1 showed a significant positive correlation with breast cancer stem cell markers such as ALDH1A1, EPCAM, ITGB1, and SOX2." (PMID 38031089, 2023). "FoxM1 has been identified as an integrin β1 transcription factor thereby promoting breast cancer progression 27, implying a possibility that USP22 controls breast cancer cell ITGB1 expression through FoxMl stabilization." (PMID 37398311, 2023). "Expression levels of ITGB1, similar to those of WAVE2, were also found to be elevated in the more aggressive basal breast cancer cell lines." (PMID 36968231, 2023). "Additional in silico analyses comparing breast cancer and adjacent normal tissue showed significantly downregulated expression of FGFR2 and ITGB1 in tumour samples." (PMID 37191822, 2023). "Comprehensive RNA sequencing data collected as a part of the MET500 cohort was analyzed for gene expression of Gli2, PTHLH, ITGB1, and ITGA2 in metastatic breast cancer samples." (PMID 34199096, 2021). "A parallel study of integrin expression in the PMC42-ET breast cancer cell line induced to undergo EMT with EGF indicated that ITGA2 and ITGB1, and their downstream regulator ILK, appeared to be upregulated." (PMID 33276802, 2020). "Several studies have demonstrated that activation of ITGB1-mediated signals induces radioresistance in HNSCC and breast cancer." (PMID 29423074, 2018). "Integrin-β1 (ITGB1) is a canonical receptor for collagen I, a central node in ECM signal transduction, and a critical mediator of breast cancer progression in mouse and in vitro models." (PMID 29162797, 2017). "Our results point toward a concerted interdependence of MMPs, ITGB1, and CDH1 that is critical for breast cancer metastasis." (PMID 28721370, 2015). "The induction of pro-apoptotic ITGB1 and ITGB3 by CuB treatment suggests activation of integrins mediated cell death by CuB in MDA-MB-231, SKBR3 and 4T-1 breast cancer cells." (PMID 24729020, 2014). "MDA-MB-231 breast cancer cell lines express high levels of ITGA2 / ITGB1, ITGA3 / ITGB1, ITGA5 / ITGB1, ITGAV / ITGB3 integrins, compared to MCF-7, T47D, and ZR75-1 breast cancer cells." (PMID 25593998, 2014). "The uptake of extracellular vesicles and/or quasi-enveloped particles is likely to be mediated by different integrins depending on the cellular background, as e.g. ITGB3 but not ITGB1 is critical for EV uptake in the breast cancer cell line MDA.MB.23179,80." (PMID 40571699, 2025). "Using this antagonist, ITGB1 and TXNDC5 proteins were downregulated, and similar results were observed for the induction of NR4A1-responsive genes CDKN1A, SERPINB5 and GADD45α in breast cancer MDA-MB-231 and SKBR3 cells." (PMID 38666927, 2024). "Indeed, western blotting analysis revealed a significant reduction in the protein expression of FoxM1, a critical transcription factor for ITGB1 expression 27, in USP22-null breast cancer cells." (PMID 37398311, 2023). "Matrine could down-regulate ITGB1 and ETM and inhibit the proliferation and migration of human breast cancer cell lines MDA-MB-231 and MCF-7." (PMID 35433636, 2022). "Then, we detected the protein expression of ITGB1 in breast cancer tissues and paired adjacent non-tumor tissues from patients diagnosed with TNBC or non-TNBC." (PMID 33747911, 2021). "ITGB1, targeted by specific miRNAs, could affect the activity of PI3K-Akt pathway in several tumors, such as breast cancer, cervical cancer and hepatocellular carcinoma." (PMID 33591944, 2021). "Although the EMT-associated ITGB1, ITGA2 and ILK are not essential for EGF-induced EMT in PMC42-ET cells, they are necessary for breast cancer cell adhesion to ECM-substrates and cellular movement." (PMID 33276802, 2020). "ITGB1 is abnormally expressed in several cancers, including LUAD and breast cancer." (PMID 33134373, 2020).
breast cancer (continued). "In contrast, in several transgenic mouse models of breast cancer, the consensus is that the CD24+/High sub-population rather than CD24Neg/Low sub-population enriches for TIC activities when CD24 is paired with either CD29 (ITGB1) or CD61 (ITGB3)." (PMID 27001172, 2016). "The activities of Itgb1 (coding for integrin β1), TGFβ2 and Vegfα are mediated, at least in part, by Cyr61 (CCN1,)–a secreted matrix protein involved in the clinical progression of breast cancer to an invasive phenotype." (PMID 19450255, 2009). "In addition to showing that ITGB1 is a target protein for bisecting GlcNAc, significant bisecting GlcNAc structures and decreased amounts of its glycosyltransferase MGAT3 were found in breast cancer cell lines, tissues, and serum." (PMID 38279122, 2024). "DepMap portal plots using publicly available data derived from human breast cancer cell lines and Gepia2 plots using publicly available tumor samples from patients with breast cancer demonstrated that TNBC subtypes show high expression levels of PTK2 (FAK), EGFR, ITGA5, ITGB1, and STAT3." (PMID 38315147, 2024). "Importantly, our in vitro and mouse preclinical findings are supported by human clinical data where increased expression of WAVE2 and ITGB1, and decreased expression levels of miR-29 and DGCR8 correlate with poor disease outcome in human patients with breast cancer tumors." (PMID 36968231, 2023). "Indeed, ITGB1 is essential for cancer chemo-resistance and metastasis mediated by aberrant actin-bundling protein in breast cancer stem cells, and its signaling foster resistance to inhibitors of HER2 and PI3K in HER2+ breast cancer." (PMID 32787954, 2020). "CD63, ITGB1, and ITGAV were abundant on the cell surface of breast cancer cells while CD11b was lacking." (PMID 35923105, 2022). "Whole exome sequencing of tumor biopsies from patients collected under the Metastatic Breast Cancer Project revealed that metastatic primary tumors have higher ITGA2 and ITGB1 copy number compared to non-metastatic primary tumors." (PMID 34199096, 2021). "Spearman correlation analysis of gene signatures in metastatic biopsies of breast cancer reveal a significant (p < 0.001) negative correlation between PTHLH and ITGA2 (p < 0.001), PTHLH and ITGB1 (p < 0.01), Gli2 and ITGA2 (p < 0.001), and Gli2 and ITGB1 (p < 0.0001)." (PMID 34199096, 2021). "Although PI3K/AKT signaling is the main reason for breast cancer development, we could not detect any spots or differences in MDA-MB-231 cells upon COL1 or/and ITGB1-kd." (PMID 32668815, 2020).
gastric cancer (42 papers, 2013 to 2025). A primary or metastatic malignant neoplasm involving the stomach. "In gastric cancer patients, hTERT expression positively correlates with ITGB1 expression, and both are associated with poor prognosis." (PMID 39871386, 2025). "Increased expression of ITGB1 promotes invasion and migration of gastric cancer cells and is associated with poor prognosis and recurrence of GAC patients." (PMID 36520032, 2023). "Next, we sought to investigate the underlying mechanism of ITGB1 associated gastric cancer progression and drugs resistance." (PMID 34319913, 2021). "Our study indicated the elevated expression of ITGB1 in gastric cancer and its’ association with collagen, which might be benefit from targeted therapies in further clinical trials." (PMID 34319913, 2021). "The survival analysis revealed that patients with high expression of ITGB1 had a shorter survival time than the patients with low ITGB1 expression, which indicates that high expression of ITGB1 is closely linked to a poor prognosis of gastric cancer." (PMID 26903137, 2016). "For instance, the hTERT/MDM2-FOXO3a-integrin β1 (ITGB1) signaling pathway is implicated in hTERT-stimulated gastric cancer invasion, suggesting that this signaling pathway may be a novel target for the prevention and treatment of gastric cancer metastasis." (PMID 38203812, 2024). "Another study reported that FTO augmented gastric cancer metastasis by upregulating ITGB1 via decreasing its m6A levels." (PMID 40002690, 2025). "On the other hand, ITGB1 has been identified as an important gene for metastasis, progression, and prognosis for pancreatic cancer, lung adenocarcinoma, and gastric cancer." (PMID 38254031, 2024). "Both ITGB1 and ITGAV play important roles promoting the invasion and migration of gastric cancer cells in vitro and are associated with poor prognostic outcomes." (PMID 36520032, 2023). "ITGB1 affects the prognosis in gastric cancer patients and plays a core role in immune suppression in gastric cancer." (PMID 35864742, 2023). "In gastric cancer, we found a correlation between ITGB1 expression and Wnt/β‐catenin signaling pathway activity." (PMID 35864742, 2023). "Integrinβ1 (ITGB1) is markedly overexpressed in various malignancies and has been reported as a prospective marker in predicting the effects of immunotherapy in gastric cancer." (PMID 36983711, 2023). "Previous studies reported that MYC which located on chr8p24.21 locus (amplified in ITGB1 high subgroup), can promote malignant progression of gastric cancer cells." (PMID 37007126, 2023). "We also found overexpression of integrin family members including ITGB1 and ITGAV, which is associated with poor overall survival of gastric cancer patients." (PMID 36520032, 2023). "A number of proteins have been reported to play important roles in gastric cancer metastasis, such as ITGB1, ITGAV, and LAMA4." (PMID 36520032, 2023). "Maspin was proven to also affect the EMT and angiogenesis of gastric cancer cells via the ITGB1/FAK pathway." (PMID 37296710, 2023). "The positive rate of ITGB1 expression in the Fudan University Shanghai Cancer Center gastric cancer tumor tissues was 61.4% (258/420) and correlated with deep invasion (p = 0.017), an advanced clinical stage (p = 0.011), and a poor prognosis (p < 0.05)." (PMID 35864742, 2023). "We aimed to explore the predictive value of β1 integrin (ITGB1) as a predictor of immunnotherapy in gastric cancer." (PMID 37667169, 2023). "FTO accelerated cell growth and metastasis via regulation of caveolin-1 and ITGB1 and metabolic regulation of mitochondrial dynamics in gastric cancer." (PMID 36003776, 2022). "As an upstream molecule of the Wnt/β-catenin signaling pathway, ITGB1 played a crucial role in immune suppression in gastric cancer." (PMID 36230417, 2022). "Together, those results suggested elevated expression of type I collagen and the positive correlation between ITGB1 and gastric cancer development." (PMID 34319913, 2021).